CTHRC1 (collagen triple helix repeat containing 1)
Description:
May act as a negative regulator of collagen matrix deposition.
Tractability: Antibody: UniProt places it where antibodies can reach, with medium confidence; UniProt predicts a signal peptide or a membrane-spanning region; its Gene Ontology location is reachable by antibodies, with medium confidence.
Gene: Protein-coding gene on chromosome 8 (103,371,538 to 103,382,990, forward strand). Ensembl gene ENSG00000164932.
Subcellular location: Secreted, extracellular space, extracellular matrix
Subcellular location (Human Protein Atlas): Nucleoplasm; Predicted to be secreted
Gene Ontology:
Molecular function: extracellular matrix structural constituent; prostaglandin-endoperoxide synthase activity; frizzled binding; Wnt-protein binding
Biological process: cyclooxygenase pathway
Cellular component: extracellular matrix; extracellular region; cytoplasm; neuron projection; non-collagenous component of interstitial matrix
Genetic constraint (gnomAD): Loss-of-function variants: 19 observed, 24.74 expected, observed/expected ratio (o/e) 0.77, 90% interval 0.54 to 1.13. The upper end of that interval is the gene's LOEUF score, 1.13, which puts it in group 4 of 6, group 1 being the genes least tolerant of losing a copy. Missense variants: 279 observed, 298.16 expected, observed/expected ratio (o/e) 0.94, 90% interval 0.85 to 1.03. Synonymous variants: 109 observed, 105.84 expected, observed/expected ratio (o/e) 1.03, 90% interval 0.88 to 1.21.
Homologues: Orthologues: chimpanzee CTHRC1 (100% identical), macaque CTHRC1 (100% identical), dog CTHRC1 (98% identical), pig CTHRC1 (96% identical), rat Cthrc1 (95% identical), mouse Cthrc1 (94% identical), guinea pig CTHRC1 (89% identical), tropical clawed frog cthrc1 (74% identical), zebrafish cthrc1a (70% identical), zebrafish cthrc1b (68% identical), Caenorhabditis elegans col-187 (7% identical), Caenorhabditis elegans col-35 (7% identical), and 10 more. Paralogues in human: METTL24 (18% identical), SCARA3 (14% identical).
Diseases named in the same sentence as CTHRC1 in open-access papers:
CTHRC1 is named in the same sentence as 148 diseases in open-access papers, as found by Europe PMC text mining. Sharing a sentence is not in itself a finding about the gene and the disease. The quoted sentences say what the papers report.
colorectal cancer (42 papers, 2014 to 2026). A primary or metastatic malignant neoplasm that affects the colon or rectum. "The association of CTHRC1 with tumor progression is demonstrated in various cancers, including melanoma, hepatocellular carcinoma, lung cancer, gastric cancer, pancreatic cancer, breast cancer, and colorectal cancer." (PMID 33564303, 2021). "Since CTHRC1 is expressed in several cancer models and has recently been implicated in vascular diseases, we hypothesized that CTHRC1 might regulate colorectal cancer tissue invasion and metastasis through modulation of MMP9." (PMID 24504172, 2014). "The results revealed that MMP11+ mCAFs predominantly overlapped with FN1+ CAFs in breast cancer, COL11A1+ CAFs in colorectal cancer, and CTHRC1+ CAFs in lung adenocarcinoma." (PMID 40552583, 2025). "In recent years, the role of CTHRC1 in cancer research has gradually emerged, especially in gastric cancer, hepatocellular carcinoma, colorectal cancer, esophageal cancer, and other cancers." (PMID 39132501, 2024). "As reported in previous studies, CTHRC1 promotes human colorectal cancer cell proliferation and invasiveness by activating the Wnt/PCP signaling pathway; CTHRC1 promotes liver metastasis of colorectal cancer through the TGF-β pathway." (PMID 39052013, 2024). "The collagen triple helix repeat containing 1 (CTHRC1) is secreted by the colorectal cancer cells, stabilizing the TGF-beta signaling and activation." (PMID 37324012, 2023). "CTHRC1 - Collagen triple helix repeat containing 1 (CTHRC1) is involved in tissue repair and is highly expressed in various malignant tumors including colorectal cancer." (PMID 38304289, 2023). "Studies have shown that CTHRC1 promotes colorectal cancer metastasis by inducing the Wnt/PCP signal transduction." (PMID 35300110, 2022). "Investigation of the alteration frequency of CTHRC1 using the TCGA database revealed approximately 7.1% gene alteration in 634 colorectal cancer cases." (PMID 35300110, 2022). "CTHRC1 promotes the proliferation of colorectal cancer by activating the Wnt/PCP signalling pathway." (PMID 35300110, 2022). "miR-155 promotes hepatocellular carcinoma progression by suppressing PTEN through the PI3K/Akt pathway and acts as a tumor suppressor by targeting CTHRC1 in vitro in colorectal cancer." (PMID 33987098, 2021). "Previous studies have shown that CTHRC1 can promote the metastasis of colorectal cancer, ovarian cancer, gastric cancer, and cervical cancer." (PMID 34195091, 2021). "In hepatoma cells, and colorectal cancer cells increased CTHRC1 activated expression of MMP-9, which is known to contribute to extracellular matrix breakdown and tumor promotion." (PMID 33717164, 2021). "In colorectal cancer, CTHRC1 can enhance Erk phosphorylation, up-regulate MMP-9 expression, and promote extracellular matrix degradation, thereby promoting tumor cell invasion." (PMID 32156314, 2020). "CTHRC1 has been reported to promote proliferation and invasiveness of human colorectal cancer cells by activating Wnt/PCP signaling." (PMID 31612481, 2020). "Given its anti-tumor effect, miR-520d-5p suppresses human glioma cell proliferation through targeting PTTG1 and inhibits tumor metastasis and growth by binding to CTHRC1 in colorectal cancer." (PMID 32950972, 2020). "The overexpression of CTHRC1 is frequently detected in several solid tumors, such as melanoma, breast ductal carcinoma, gastric cancer, hepatocellular carcinoma and colorectal cancer." (PMID 31798347, 2019). "In this study, we aimed to investigate the clinical significance and possible role of CTHRC1 in the process of epithelial‐mesenchymal transition (EMT) in colorectal cancer (CRC)." (PMID 30302922, 2018). "Sp1-mediated microRNA-520d-5p suppresses tumor growth and metastasis in colorectal cancer by targeting CTHRC1." (PMID 28422727, 2017). "CTHRC1 is upregulated and enhances the epithelial-mesenchymal transition of tumor cells to promote cancer invasion and metastasis in colorectal cancer and melanoma." (PMID 28678795, 2017).
colorectal cancer (continued). "CTHRC1 has shown to be abundantly expressed in human pancreatic cancer tissues, hepatocellular carcinoma, gastric cancer, colorectal cancer, and gastrointestinal stromal tumors." (PMID 29285247, 2017). "All these results indicate that CTHRC1 plays a pivotal role in promoting the progression of colorectal cancer." (PMID 28854193, 2017). "It has been shown that Sp1 acts as a tumor suppressor to suppress colorectal cancer growth and metastasis by increasing miRNA‐52d‐5p transcription for target CTHRC1." (PMID 28846829, 2017). "In this study, we identified CTHRC1 as a colorectal cancer-related gene whose expression is regulated by an epigenetic mechanism, namely DNA methylation." (PMID 24504172, 2014). "In conclusion, we demonstrated that CTHRC1 is highly expressed in colorectal cancer and its expression is correlated with unfavorable clinicopathologic features and methylation status." (PMID 24504172, 2014). "The expressions of MMP9 was weakly correlated to the expressions if CTHRC1 in colorectal cancer tissue (R=0.171, p=0.019)." (PMID 24504172, 2014). "We also examined the basal expression level of CTHRC1 in primary fibroblast and human colorectal cancer cell lines such as HT-29, SW480, DLD-1, KM12C, and KM12SM by Western blot analysis and laser confocal microscope." (PMID 24504172, 2014). "In the present study, we demonstrated using microarray analysis that CTHRC1 is a colorectal cancer-related protein that is differentially expressed between human normal and tumor patient tissues." (PMID 24504172, 2014). "Similarly, Oncomine analysis of the pathological samples showed that the transcriptional levels of CTHRC1 mRNA were significantly up-regulated in various cancer types including colorectal cancer." (PMID 35300110, 2022). "CTHRC1 binds TGFß and promotes its activation in colorectal cancer cells." (PMID 36190948, 2022). "Previous studies showed that CTHRC1 promoted tumor cell progression and might play a key role in the invasion metastasis of cervical carcinoma, cervical squamous cell carcinoma, and colorectal cancer." (PMID 34512711, 2021). "In addition, miR-520d-5p functions as an anti-oncogene in colorectal cancer and suppresses tumor growth and metastasis via regulating CTHRC1." (PMID 34353336, 2021). "MiR-520d-5p represses metastasis and tumor growth via targeting CTHRC1 in colorectal cancer." (PMID 34434890, 2021). "Previous studies have shown that CTHRC1 is highly expressed in a variety of tumors and can be a prognostic factor for non-small cell lung cancer, liver cancer, gastrointestinal stromal tumor, pancreatic cancer, and colorectal cancer." (PMID 32156314, 2020). "Additionally, some reports have demonstrated that patients with higher CTHRC1 levels tend to have poor prognosis in many tumors, such as Wilm’s tumor, esophageal squamous cell carcinoma, colorectal cancer and cervical squamous cell carcinoma." (PMID 31798347, 2019). "Moreover, CTHRC1 promoted colorectal cancer cell invasiveness through activation of ERK and subsequent induction of MMP9 expression." (PMID 29285247, 2017). "Many studies have investigated the role of CTHRC1 in colorectal cancer." (PMID 28854193, 2017). "We also used immunohistochemistry to investigate the possibility that CTHRC1 protein might be a prognostic marker CTHRC1 was detected slight expression levels in normal mucosal epithelial cells and colorectal cancer lesions." (PMID 24504172, 2014). "In the current study, we showed for the first time that CTHRC1 is an epigenetic target in colorectal cancer and that the frequent upregulation of CTHRC1 observed in colon cancer may be due to a CpG demethylation event in the exon 1 region of the gene." (PMID 24504172, 2014). "With this data of immune-expression in colorectal cancer tissues, it is very difficult to speculate the close mechanism between CTHRC1 and MMP9." (PMID 24504172, 2014).
colorectal cancer (continued). "To explore differentially expressed genes between normal tissue and colorectal cancer tissue, we performed a microarray analysis on 66 tumor samples and 9 normal samples using a 48K Illumina oligonucleotide chip (Illumina Inc.), identifying CTHRC1 as a gene upregulated in colorectal cancer." (PMID 24504172, 2014). "Collagen triple helix repeat-containing 1 (CTHRC1) is known to be aberrantly upregulated in most human solid tumors, although the functional roles of CTHRC1 in colorectal cancer remain unclear." (PMID 24504172, 2014). "The elevated levels of CTHRC1 in colorectal cancer patients could suggest an important role of this protein in tumor progression." (PMID 24504172, 2014). "Thus, ANOS1 and CTHRC1 genes promote the development and metastasis of colorectal cancer." (PMID 28854193, 2017). "Colorectal cancer (CRC), a highly prevalent epithelial malignancy, sees CTHRC1 influencing tumor progression and metastasis through its modulation of several downstream signaling cascades, such as Wnt/PCP, TGF-β/Smad, and MEK/ERK pathways." (PMID 40201173, 2025). "In colon cancer, CTHRC1 remodels infiltrating macrophages through interaction with TGF-β receptors, promoting liver metastasis of colorectal cancer cells." (PMID 39132501, 2024). "Collagen triple helix repeat containing 1 (CTHRC1) embedded in the Wingless and Int-1/Planar cell polarity (WNT–PCP) pathway, Netrin-1 (NTN1), and deleted in colorectal carcinoma (DCC) provides for SC migration." (PMID 35408800, 2022). "The expressions between CTHRC1 and MMP9 in colorectal cancer tissues revealed the weak correlations." (PMID 24504172, 2014). "Another study suggested that CTHRC1 upregulated MMP9 via ERK activation in colorectal cancer; however, alteration in MMP9 expression was not indicated in our RNA sequencing data." (PMID 28645305, 2017). "CTHRC1 was documented as a prognostic predictor in many cancers such as Gastrointestinal Stromal Tumors (GIST), non-small cell lung cancer (NSCLC), gastric cancer, and colorectal cancer." (PMID 26452130, 2015). "However, the regulation and function of CTHRC1 in colorectal cancer and its relationship with tumor progression have not been reported." (PMID 24504172, 2014).
gastric cancer (37 papers, 2010 to 2025). A primary or metastatic malignant neoplasm involving the stomach. "CTHRC1, which is found in high levels in various human solid tumors including gastric cancer, has been shown to have a significant association with the infiltration of macrophages." (PMID 40296906, 2025). "The pooled result showed that positive expression of CTHRC1 was associated with poor prognosis of gastric cancer patients." (PMID 35910202, 2022). "To verify the correlation between CTHRC1 and angiogenesis, we constructed co-expression analysis between CTHRC1 and some angiogenesis associated markers in gastric cancer using the TCGA dataset." (PMID 35928443, 2022). "The software “Metascape” was adopted in order to evaluate the function of CTHRC1-associated DEGs in gastric cancer patients." (PMID 35928443, 2022). "To better understand the relevance and underlying mechanisms of CTHRC1 expression, we investigated the relationship between the CTHRC1 expression and clinical characteristics of gastric cancer samples." (PMID 35928443, 2022). "Accordingly, it has been reported that upregulation of CTHRC1 by TGF-β1 was associated with metastasis in human gastric cancer." (PMID 29285247, 2017). "Evaluation of human gastric cancer samples demonstrated that PRR11 expression was also associated with increased CTHRC1 and decreased LXN expression." (PMID 26252227, 2015). "In addition, the CTHRC1 high group was associated with worse prognosis in gastric cancer patients in both univariate and multivariate analysis." (PMID 35928443, 2022). "CTHRC1 is upregulated by promoter demethylation and transforming growth factor-β1 and may be associated with metastasis in human gastric cancer." (PMID 35664061, 2022). "CTHRC1 may be associated with metastasis in human gastric cancer." (PMID 31992202, 2020). "After identifying these prognostic genes, including CPZ, CTHRC1, DKK1, EGF, and GPC3, we will explore their specific impact on gastric cancer progression, as well as the molecular mechanisms underlying it, particularly the CPZ." (PMID 40296906, 2025). "We highlighted genes, including TPX2, MKI67, EXO1, and CTHRC1, as potential biomarkers for early diagnosis, prognostic evaluation, and therapeutic targeting in gastric cancer." (PMID 40445003, 2025). "Studies have demonstrated the involvement of CTHRC1 in gastric cancer metastasis and hepatocellular carcinoma metastasis." (PMID 40134434, 2025). "CTHRC1 is notably upregulated in gastric carcinoma tissues compared to normal gastric tissues, with its elevated expression correlating with advanced stages of the disease, including deeper tumor invasion and lymph node metastasis." (PMID 40978044, 2025). "In previous studies, Zhao found that CTHRC1 was related to several pathways in gastric cancer, including extracellular matrix organization and vascular development, through enrichment analysis." (PMID 38937712, 2024). "Previous studies indicate that fibroblasts with high CTHRC1 and POSTN expression are markers for gastric cancer-associated fibroblasts." (PMID 39850884, 2024). "The prognostic value of CTHRC1 has also been found in other tumors, such as colon adenocarcinoma, gastric cancer, breast cancer and kidney renal clear cell carcinoma." (PMID 38937712, 2024). "CTHRC1 overexpression has been observed in various solid human malignant tumors, including melanoma, gastric cancer, colorectal cancer, breast cancer, and thyroid cancer." (PMID 37273536, 2023). "Although CTHRC1 was a promising target for several cancer diseases, its specific role and mechanism with immune infiltrates in gastric cancer are still unclear." (PMID 35928443, 2022). "Here, we systematically investigated the expression status and prognostic value of CTHRC1 in gastric cancer by integrating the Cancer Genome Atlas (TCGA), Gene Expression Omnibus (GEO) and Genome Sequence Archive (GSA) datasets." (PMID 35928443, 2022).